GLI1 (GLI family zinc finger 1)
Diseases named in the same sentence as GLI1 in open-access papers (continued):
Sharing a sentence is not in itself a finding about the gene and the disease.
renal fibrosis (16 papers, 2015 to 2025). A final common manifestation of a wide variety of chronic kidney diseases characterized by glomerulosclerosis and tubulointerstitial fibrosis. "Gli1 activation was observed in myofibroblasts, and Gli1+ cell‐specific YAP/TAZ knockout by tamoxifen treatment was reported to ameliorate the development of renal fibrosis following unilateral ureteral obstruction." (PMID 40133213, 2025). "During CKD, the Hedgehog signaling pathway is essential in renal fibrosis development, primarily through the secretion of Hh ligands by epithelial cells and the upregulation of Gli1 in myofibroblasts." (PMID 40563434, 2025). "To further elucidate the role of GLI1 in GABP‐mediated renal fibrosis in a murine model of diabetic nephropathy, we administered the GLI1 inhibitor GANT61 subcutaneously at a dosage of 30 mg kg−1 to both db/m‐OE and db/db mice." (PMID 39985381, 2025). "Second, we explored the mechanism of GABP‐mediated GLI1 regulation in DN renal fibrosis using biological techniques, such as transcriptomics." (PMID 39985381, 2025). "The pharmacological blockade and genetic ablation of GLI1 or GLI2 in these MSCs ameliorated renal fibrosis." (PMID 39766192, 2024). "Utilizing single-cell transcriptomics, TNF from activated leukocytes drove Gli1+ cell proliferation and fostered renal fibrosis by elevating Indian Hedgehog (IHH) release from TECs." (PMID 38770013, 2024). "We next confirmed that ethanol induced renal fibrosis in gli1-LacZ mice as well as wild-type animals to find that accumulation of fibrillar collagen 1 in response to this stress was identical to its induction by ethanol catabolism in wild-type mice." (PMID 26720402, 2015). "We show acute kidney inflammation resulting from chronic ingestion of the common xenobiotic ethanol initiates Gli1 transcription and hedgehog synthesis in kidney pericytes, and promotes renal fibrosis." (PMID 26720402, 2015). "Gli1‐expressing cells have been shown to differentiate into myofibroblasts during renal fibrosis." (PMID 40133213, 2025). "GABP regulates GLI1 target genes and affects DN renal fibrosis through GLI1." (PMID 39985381, 2025). "The genetic ablation of Gli1 reduces kidney injury in mouse models of renal fibrosis." (PMID 40563434, 2025). "In addition, researchers investigated the link between GLI1 and GLI2 mRNA expression and the extent of renal fibrosis in 10 human specimens, finding that increased GLI1 and GLI2 expression corresponded to a greater degree of fibrosis." (PMID 39766192, 2024). "Reduction of renal fibrosis, normalising renal function, and decreasing the expression of fibronectin (FN), Collagen I, α-SMA, EMT, Shh, Gli-1, and E-cadherin." (PMID 40427522, 2025). "Furthermore, using transgenic Gli-CreERt2;tdTomato 10-day UUO mice, they showed that Gli1-positive cells proliferate within the interstitial area and express αSMA, indicating perivascular Gli1+ mesenchymal-like cells to be a major cellular origin of renal fibrosis." (PMID 37440209, 2023). "Through the study of Gli1-lacZ knockout rats, it has been revealed that the SHH-Gli1 pathway is essential in renal fibrosis." (PMID 35190746, 2022). "The in vivo study aimed to investigate the pathological changes of renal fibrosis, and the effects of rhein on the expression of SHH, Gli1, and Snail proteins were analyzed." (PMID 35966731, 2022). "Their study proved that HSP decreased the expression of fibronectin (FN), Collagen I, α-SMA, EMT, Shh, Gli-1, deceased E-cadherin expression, reducing renal fibrosis normalize the renal function." (PMID 35128104, 2022). "Moreover, HSP reduced renal fibrosis, normalised renal function in the (NRK)-52E cell line and UUO-mouse model, and decreased the expression of fibronectin (FN), Collagen I, α-SMA, EMT, Shh, Gli-1, and E-cadherin." (PMID 40427522, 2025).
renal fibrosis (continued). "We conclude that renal fibrosis after pyelonephritis is exacerbated by the presence of androgens and involves activation of the TGFβ1 signaling cascade, leading to increases in cortical populations of MSC‐like cells and the Gli1 + activated myofibroblasts that are responsible for scarring." (PMID 32227630, 2020).
liver cancer (15 papers, 2012 to 2024). An epithelial or non-epithelial malignant neoplasm that arises from the liver. "Disrupting this binding or reducing the level of Rab23 has a significant impact on the expression and nuclear localization of Gli1 in human liver cancer cell line Hep3B and HepG2, ultimately leading to suppression of cell growth." (PMID 37884351, 2024). "circIPO11 recruits TOP1 to GLI1 promoter to activate its transcription, and drives self-renewal of liver cancer initiating cells." (PMID 36747292, 2023). "HBx protein stimulates the HH-GLI activation through protein stabilization and nuclear localization of GLI1 in liver cancer cells while the exact role of GLI1 protein translocation for these viral activities remains to be discovered." (PMID 33494284, 2021). "The MTS assay showed that the proliferation rates of CD90+ liver cancer cells transfected with Gli1 or Gli3 siRNA were significantly decreased in comparison with the negative control." (PMID 29722127, 2018). "The correlation of CD90 expression with Gli1 (R = .1442, P = .3128) and Gli3 (R = .2786, P = .0477) was also validated by these expression results in clinical liver cancer tissues." (PMID 29722127, 2018). "For further validation of the correlation expression of CD90, Gli1 and Gli3 in liver cancer cells, the expression levels of these 3 genes among 51 pairs of liver cancer tissues and corresponding adjacent normal tissues were analysed by quantitative RT‐PCR." (PMID 29722127, 2018). "More importantly, the in vivo tumorigenicity assay showed that the sizes and weights of tumours originating from CD90+ liver cancer cells with suppressed Gli1 or Gli3 expression were markedly reduced compared with the negative control." (PMID 29722127, 2018). "CD90 expression exhibited a high positive correlation with Gli1 and Gli3 in multiple liver cancer cell lines and human cancerous liver tissues, both of which showed a significant increase in liver cancer." (PMID 29722127, 2018). "More importantly, the expression of Gli1 and Gli3 showed similar expression patterns in these liver cancer cell lines." (PMID 29722127, 2018). "The stem cell potentials of CD90+ 97L liver cancer cells were greatly impaired by Gli1/3 knockdown with siRNA but enhanced by SHH treatment." (PMID 29722127, 2018). "These molecular and cellular assays fully validated that the stem cell properties of CD90+ liver cancer cells were mediated by Gli1 and Gli3 expression." (PMID 29722127, 2018). "After siRNA transfection, the expression of Gli1 and Gli3 showed a significant decrease compared with the negative control, demonstrating the efficient knockout of gene expression in liver cancer cells." (PMID 29722127, 2018). "Together, our findings demonstrate a central role for GLI1 in regulation of the EMT in liver cancer and expand the repertoire of pathways that modulate this cellular process." (PMID 23185371, 2012). "Furthermore, the expression levels of the major SHH pathway proteins Smoothened (SMO) and GLI‐1 were also significantly reduced in shRab23 liver cancer cells compared to the control." (PMID 37884351, 2024). "Additionally, the positive correlation of CD90 expression with Gli1 (R = .5347, P < .0001) and Gli3 (R = .4529, P < .0001) was also validated by these expression results in liver cancer tissues." (PMID 29722127, 2018). "Similarly, the transwell assay showed that the migration rates of CD90+ liver cancer cells were remarkably suppressed by transfection with Gli1 and Gli3 siRNAs." (PMID 29722127, 2018). "Moreover, the sphere formation capacity of CD90+ liver cancer stem cells was also greatly inhibited by depletion of Gli1 and Gli3 expression As." (PMID 29722127, 2018). "For a more reliable correlation of CD90, Gli1 and Gli3 expression levels with liver cancer progression, pathological data from the Cancer Genome Atlas (TCGA) containing expression profiles of 365 liver cancer patients were further analysed as described in the Material and Methods section." (PMID 29722127, 2018).
liver cancer (continued). "Multiple liver cancer cell lines and human HCC tissues have shown a strong correlation between CD90 expression and increased expression of GLI-1 and GLI-3." (PMID 38730691, 2024). "Our quantitative RT‐PCR and Western blotting experiments showed that the expression of CD90 was also significantly down‐regulated by knockdown of Gli1 and Gli3 expression in CD90+ liver cancer cells." (PMID 29722127, 2018). "We then re‐assessed the expression levels of Gli1 and Gli3 among these cancer tissues with high CD90 expression and observed elevated Gli1 and Gli3 expression in high‐CD90 liver cancer tissues." (PMID 29722127, 2018). "Consistent results were observed in CD90+ liver cancer cells treated with SHH, which were completely reversed compared with those transfected with Gli1 or Gli3 siRNA." (PMID 29722127, 2018). "In contrast, knockdown of Gli1 and Gli3 significantly down‐regulated IL‐6, phosphorylated JAK2, phosphorylated STAT3protein abundances in CD90+ 97L liver cancer cells." (PMID 29722127, 2018). "Functional analysis was conducted by siRNA‐mediated CD90, Gli1 and Gli3 gene knockdown, SHH treatment and application of the JAK2 inhibitor AZD1480 and IL6 neutralizing antibody in CD90+ liver cancer stem cells, followed by cell proliferation, migration, sphere formation and tumorigenicity assays." (PMID 29722127, 2018).
lymph node metastasis (15 papers, 2008 to 2023). "Meanwhile, Gli1 expression was significantly associated with tumor size (P = 0.039), the depth of tumor invasion (P = 0.001), lymph node metastasis (P = 0.004), and TNM stage (P = 0.004)." (PMID 27836001, 2016). "In our study, we showed that positive staining for SHH and GLI1 was associated with advanced stage, lymph node metastasis and poor differentiation in NB specimens via IHC analysis." (PMID 25811359, 2015). "Furthermore, the data demonstrated that Shh, Ptch1, Smo and Gli1 overexpression was markedly associated with a higher incidence of Lymph node metastasis and a more advanced TNM stage in GC (P<0.05)." (PMID 32328197, 2020). "The multivariate Cox regression analysis revealed that pT stage, lymph node metastasis, distant metastasis, and Gli1 expression (all P < 0.05) were independent prognostic predictors for OS." (PMID 32430068, 2020). "The univariate Cox regression analysis showed that tumor size, pT stage, lymph node metastasis, distant metastasis, and Gli1 expression (all P < 0.05) were independent prognostic factors for poor OS." (PMID 32430068, 2020). "In LAD, the overexpression of nuclear Gli-1 was positively correlated with lymph node metastases, implying a promoter role for activated Gli-1 in LAD progression and metastases." (PMID 26462018, 2015). "Gli1 has been reported as highly expressed in GC and positively correlated with lymph node metastasis." (PMID 24443799, 2014). "All patients with Gli-1 nuclear expression (10.1%) had distant or lymph-node metastasis, and six out of seven died within 13 months." (PMID 18475300, 2008). "All patients with Gli-1 nuclear expression had distant or lymph-node metastasis, and six of the seven died within 13 months." (PMID 18475300, 2008). "Subgroup analysis indicated that patients with Gli1 positive expression could have a significant poorer survival than others at the same depth of tumor invation (stage T3-T4), lymph node metastasis (positive) or same TNM stage (stage III-IV)." (PMID 29321573, 2018). "In univariate analysis, the median overall survival (OS) was associated with histological differentiation, invasion depth, lymph node metastasis, TNM stage and the expression of Shh, Ptch1, Smo and Gli1 (P<0.05)." (PMID 32328197, 2020). "Tumors with lymph node metastasis showed higher frequency of SHH and GLI1 positivity (SHH: 79% vs. 51%, P = 0.013; GLI1: 68% vs. 43%, P = 0.039)." (PMID 25811359, 2015). "Similarly, our analysis indicates that Gli-1 overexpression not only promotes higher TNM stage and lymph node metastasis strongly but also reduces OS and DFS/RFS in GC patients." (PMID 33639931, 2021). "Furthermore, multivariate survival analysis demonstrated that lymph node metastasis, TNM stage and a positive expression of Gli1 were independent prognostic factors for OS (P<0.05)." (PMID 32328197, 2020). "Overall survival (OS) was significantly associated with lymph-node metastasis, distant metastasis, and CRT, and was further correlated with the absence of both Gli-1 nuclear expression and residual tumour." (PMID 18475300, 2008). "Gli1 significantly correlated with tumor grade (P = 0.001), pT stage (P = 0.029), clinical stage (P = 0.005), distant metastasis (P = 0.007), and gross type (P = 0.021), not with age, sex, tumor location, tumor size, lymph node metastasis, histological type." (PMID 32430068, 2020).
renal cell carcinoma (14 papers, 2016 to 2025). "The aim of the present study is to explore the potential role of GLI1 in p21 mediated cell cycle arrest induced by capsaicin treatment in renal cell carcinoma (RCC) 786-O and Caki-1 cell lines." (PMID 41323789, 2025). "In contrast, mRNA analysis of the elements of the Hedgehog signaling pathway, such as SHH, SMO, and GLI1 in tissue from renal cell carcinoma showed higher expression levels than healthy tissue, while an underexpression of PTCH1 was observed and specifically in patients older than 60 years." (PMID 38287479, 2024). "In addition, in renal cell carcinoma cells both GLI1 and GLI2 are activated by the PI3K/AKT signaling." (PMID 30934935, 2019). "A more recent paper showed that GLI1 and GLI2 were activated by Insulin like growth factor (IGF-1)-mediated activation of the PI3K/AKT pathway in renal cell carcinoma." (PMID 33081032, 2020). "Recently, PI3K/Akt mediated non-canonical activation of GLI1 has also been shown in renal cell carcinoma." (PMID 28380428, 2017). "PI3K/AKT can activate GLI1 and GLI2 through the non-classical Hh signaling pathway to enhance renal cell carcinoma's proliferation and clonogenic ability." (PMID 38498906, 2024).
esophageal squamous cell carcinoma (13 papers, 2008 to 2025). Esophageal squamous cell carcinoma (ESCC) is a type of esophageal carcinoma (EC) that can affect any part of the esophagus, but is usually located in the upper or middle third. "Mechanistically, PRMT1 methylates the DNA-binding domain (DBD) of Gli1, known as glioma-associated oncogene homolog 1, thereby potentiating its transcriptional activity, promoting the growth and migration of esophageal squamous cell carcinoma cells." (PMID 38326807, 2024). "In addition, overexpression of GLI1 was correlated to the lymph node metastasis in esophageal squamous cell carcinoma (ESCC) patients." (PMID 29706061, 2018). "The current study retrospectively investigated the expression of Gli-1 protein in human oesophageal squamous cell carcinoma (ESCC) tissues, and evaluated the clinical implications of Hh signal activation for these patients who underwent preoperative CRT and radical surgery." (PMID 18475300, 2008). "Moreover, PTTG1 promotes the invasion of esophageal squamous cell cancer cells by inducing epithelial–mesenchymal transformation, and PTTG1 is involved in inducing epithelial–mesenchymal transformation by activating the expression of GLI1 in esophageal squamous cell carcinoma." (PMID 33123466, 2020).
mesenchymal tumors (13 papers, 2016 to 2026). "Molecular events associated with GLI1-altered mesenchymal tumors include GLI1 gene fusion and amplification." (PMID 39995845, 2025). "In the absence of GLI1 molecular testing, GLI1 immunohistochemistry can serve as a valuable diagnostic adjunct, aiding in the differentiation of GLI1-altered mesenchymal tumors." (PMID 39995845, 2025). "Glioma-associated homologue-1 (GLI1)-altered mesenchymal tumours are defined gene fusions or amplification of the GLI1 gene." (PMID 41035732, 2025). "Glioma-associated oncogene (GLI1)-altered mesenchymal tumors are a newly described entity of neoplasms with very few case reports published in the literature." (PMID 39720383, 2024). "Glioma-associated oncogene (GLI1)-altered mesenchymal tumors are a newly described class of tumors with molecular alterations of the GLI1 gene, usually fusions or amplifications." (PMID 39720383, 2024). "GLI1-rearranged enteric tumors are a newly proposed category of mesenchymal neoplasms, most commonly found in the gastrointestinal tract, and are defined by rearranging the GLI1 gene at chromosome 12q13.3 with various pathogenic fusion partners, most commonly ACTB::GLI1 and MALAT1::GLI1." (PMID 39851545, 2025). "The presence of SSTR2A staining in GLI1-altered mesenchymal tumors is a diagnostic pitfall that may lead to an erroneous diagnosis, especially in tumors arising in head and neck locations." (PMID 39720383, 2024). "GLI1-altered mesenchymal tumors are exceptionally rare mesenchymal tumors, with recent molecular studies implicating GLI1 gene fusion or amplification." (PMID 41888999, 2026). "GLI1-altered mesenchymal tumors represent a rare category of soft tissue tumors that have recently been incorporated into the classification of head and neck soft tissue tumors in the fifth edition of the World Health Organization (WHO) classification." (PMID 39995845, 2025). "GLI1-altered mesenchymal tumors are rare neoplasms characterized by distinct morphological and molecular features, primarily found in the head and neck, although they can also occur in other anatomical locations." (PMID 39995845, 2025). "New disease entities have been emerging based on molecular pathological findings, such as pseudoendocrine sarcoma and mesenchymal neoplasm with GLI1 gene alterations, which resemble well-differentiated neuroendocrine tumors." (PMID 40248085, 2025). "These morphological and molecular findings support the diagnosis of a GLI1-altered (PTCH1-GLI1 fusion) mesenchymal tumor." (PMID 39995845, 2025). "Most GLI1-altered mesenchymal tumors demonstrate an indolent clinical course following complete surgical resection." (PMID 39995845, 2025). "NGS revealed a PTCH1-GLI1 fusion and the combined morphology consistently pointed to GLI1-altered mesenchymal tumor." (PMID 39995845, 2025). "In the fifth edition of the WHO Classification of Head and Neck Tumors, this tumor type was included and renamed GLI1-altered mesenchymal tumors." (PMID 39995845, 2025). "GLI1-altered mesenchymal tumors display complex and variable morphological structures and cytological features." (PMID 39995845, 2025). "The possibility of a mesenchymal neoplasm with GLI1 gene alterations was raised because of GLI1 mRNA and protein overexpression." (PMID 40248085, 2025). "In this report, we present the first documented case of a GLI1-altered mesenchymal tumor arising in the pleura." (PMID 39995845, 2025). "This case expands the understanding of GLI1-altered mesenchymal tumours, especially in uncommon sites like the pleura, and highlights the importance of multidisciplinary decision-making." (PMID 41035732, 2025). "GLI1‐altered mesenchymal tumors often manifest in the head and neck, particularly within the tongue." (PMID 39776317, 2025). "We discuss the clinical perspective of a 25-year-old patient with a GLI1-altered mesenchymal tumour of the pleura." (PMID 41035732, 2025).